PGS1 (phosphatidylglycerophosphate synthase 1)
Description:
Functions in the biosynthesis of the anionic phospholipids phosphatidylglycerol and cardiolipin.
Synonyms: DKFZP762M186
Tractability: Antibody: the Human Protein Atlas places it where antibodies can reach. PROTAC: ubiquitination databases record sites on it; its protein half-life has been measured.
Gene: Protein-coding gene on chromosome 17 (78,378,637 to 78,425,114, forward strand). Ensembl gene ENSG00000087157.
Subcellular location: Mitochondrion
Subcellular location (Human Protein Atlas): Vesicles; Cell Junctions; Mid piece; Plasma membrane
Pathways (Reactome):
Metabolism: Synthesis of PG
Gene Ontology:
Molecular function: calcium ion binding; CDP-diacylglycerol-glycerol-3-phosphate 3-phosphatidyltransferase activity; catalytic activity
Biological process: cardiolipin biosynthetic process; diacylglycerol metabolic process; phosphatidylglycerol biosynthetic process
Cellular component: endoplasmic reticulum; mitochondrion; mitochondrial inner membrane; mitochondrial matrix
Genetic constraint (gnomAD): Loss-of-function variants: 40 observed, 52.19 expected, observed/expected ratio (o/e) 0.77, 90% interval 0.59 to 1. The upper end of that interval is the gene's LOEUF score, 1, which puts it in group 4 of 6, group 1 being the genes least tolerant of losing a copy. Missense variants: 651 observed, 706.29 expected, observed/expected ratio (o/e) 0.92, 90% interval 0.86 to 0.98. Synonymous variants: 320 observed, 303.84 expected, observed/expected ratio (o/e) 1.05, 90% interval 0.96 to 1.15.
Homologues: Orthologues: chimpanzee PGS1 (99% identical), guinea pig PGS1 (96% identical), dog PGS1 (96% identical), rat Pgs1 (95% identical), mouse Pgs1 (94% identical), pig PGS1 (93% identical), macaque PGS1 (86% identical), rabbit PGS1 (69% identical), tropical clawed frog pgs1 (68% identical), zebrafish pgs1 (62% identical), Drosophila melanogaster PGS1 (40% identical), Caenorhabditis elegans pgs-1 (31% identical).
Diseases named in the same sentence as PGS1 in open-access papers:
PGS1 is named in the same sentence as 16 diseases in open-access papers, as found by Europe PMC text mining. Sharing a sentence is not in itself a finding about the gene and the disease. The quoted sentences say what the papers report.
cognitive decline (2 papers, 2022 to 2025). "We further found that three proteins, i.e., IDS, FHR1, and PGS1, were independently associated with faster global cognitive decline even after considering the presence of AD in the models." (PMID 35326481, 2022).
Sepsis (2 papers, 2022 to 2024). Sepsis is defined as life-threatening organ dysfunction caused by a dysregulated host response to infection. "Currently, there remains a limited number of reports regarding the role of PGS1 in sepsis and septic-related diseases." (PMID 39609718, 2024). "Another study using GEO data identified SH3GLB1, PGS1, and RAB31 as diagnostic markers for pediatric sepsis, a possible risk factor for KD pathogenesis." (PMID 36042431, 2022).
COVID-19 (1 paper, 2025). A disease caused by infection with severe acute respiratory syndrome coronavirus 2. "Within the dataset analyzed in this study, 4 out of 27 genes (14,8%) showed the 3′UTR shortening mechanism via APA (Δusage < −0.3), providing specific examples of potential escape from miRNA regulation in COVID-19 patients: CCNG2, PGS1, RTF1 and SPCS3." (PMID 41168347, 2025).
gliosarcoma (1 paper, 2018). A rare histological variant of glioblastoma (WHO grade IV) characterized by a biphasic tissue pattern with alternating areas displaying glial and mesenchymal differentiation (WHO). "We identified additional cases of both primary (PGS1 and PGS2) and secondary gliosarcoma (SGS2 and SGS3) with a matching primary GBM (GBM2 and GBM3, respectively) from the neuropathology archives." (PMID 29416795, 2018).
Miscarriage (1 paper, 2017). A pregnancy that ends at a stage in which the fetus is incapable of surviving on its own, defined as the spontaneous loss of a fetus before the 22th week of pregnancy. "With small numbers, a younger woman had a 0.683 times (P = 0.2028, PGS1) and 0.647 times (P = 0.1231, PGS2) higher chance of a clinical miscarriage than older women." (PMID 28666459, 2017).
ovarian carcinoma (1 paper, 2021). A malignant neoplasm originating from the surface ovarian epithelium. "Among the PPI networks of SYNE1, CDK12, and PGS1, the ovarian and other cancer-related gene SYNE1 is located 19 kb downstream of ESR1, and it partially contributes to ovarian cancer." (PMID 34763659, 2021).
septic shock (1 paper, 2024). Shock caused by infection; frequently caused by gram negative bacteria, although some cases have been caused by other bacteria, viruses, fungi, and protozoa; characterized by fever, chills, tachycardia, tachypnea, and hypotension. "In this study, we recognized four immune-mitochondrial key genes (PGS1, C6orf136, THEM4, and EPHX2) in septic shock and designed a novel gene diagnosis model that provided a new and meaningful way for the diagnosis of septic shock." (PMID 39609718, 2024).
infection (3 papers, 2014 to 2024). The state of being infected such as from the introduction of a foreign agent such as serum, vaccine, antigenic substance or organism. "Thus, the comparison here focuses only on all-stage resistance genes that caused full resistance in the field (< 5% infection) as observed in other experiments with Pgs1-resistant material in the same location with the same rust isolates (data not shown)." (PMID 33688982, 2021). "The result showed that during ALV-J infection, the levels of ASAH1, NAAA, CHKA, PGS1, SGPP1, DEGS2, and SMPD1 genes were significantly increased with infection time." (PMID 38598912, 2024). "For the resistance gene Pgs1, it was observed that the resistance in the field can reduce the infection almost to zero infection when no virulent isolate occurs." (PMID 33688982, 2021).
gastrointestinal disorders (1 paper, 2024). "In the present study, Etnppl gene was found to be positively correlated with Pgs1 and Gpat3 protein in T2DM -induced gastroenteropathy, with elevated levels of Pgs1 and Gpat3 protein expression." (PMID 39211388, 2024).
PGS1 also shares sentences with these, for which no sentence is quoted: cancer (2 papers); diabetes (1); glioblastoma (1); glioma (1); leukodystrophy (1); lipid metabolism disorders (1); uveitis (1).